FHL2 (four and a half LIM domains 2)
Diseases named in the same sentence as FHL2 in open-access papers (continued):
Sharing a sentence is not in itself a finding about the gene and the disease.
cancer (41 papers, 2008 to 2025). A tumor composed of atypical neoplastic, often pleomorphic cells that invade other tissues. "An increasing number of studies have been conducted to investigate the association between FHL2 and malignant tumors." (PMID 40482916, 2025). "FHL2 has been implicated in many forms of cancers in which its expression was found to be deregulated." (PMID 25121502, 2014). "Several studies have associated high level and nuclear expression of FHL2 with the aggressiveness of cancer and bad prognostic." (PMID 20442768, 2010). "An increase in the expression of FHL2 along with β-catenin mutation suggests that FHL2 may be possibly involved in transactivating the β-catenin signaling in cancer cells." (PMID 31511432, 2019). "Because FHL2 has been previously implicated in cancer cell growth and metastasis, we investigated whether a correlation exists between FHL2 and FOXK1 expression in CRC." (PMID 27892920, 2016). "Interestingly, the expression level of FHL2 is also associated with the development of cancer." (PMID 36004205, 2022). "Pan-cancer analyses of FHL2 expression reveal a notable upregulation in certain malignant tumors, including CHOL, COAD, ESCA, HNSC, LUAD, LUSC, and PAAD." (PMID 40482916, 2025). "The dual roles of FHL2 as an oncogene or tumor suppressor in different cancer types suggest that its functional context is highly dependent on tissue type and interacting partners." (PMID 40482916, 2025). "Here, we discuss recent work on FHL2 functions as a mechanotransducer for cell proliferation as it relates to cancer cell dynamics in a mechanical environment." (PMID 39129787, 2024). "Regarding the relationship between FHL2 and cancer phenotypes, the expression level of the FHL2 gene is upregulated in metastatic cell lines." (PMID 39129787, 2024). "Conversely, the dysregulation of FHL2 has been shown in different pathological conditions, including wound healing, inflammation, and cancer." (PMID 37834391, 2023). "The 4-and-a-half LIM domain protein 2 (FHL2) is an oncogenic gene, which promotes the proliferation, invasion, and metastasis of cancer cells." (PMID 36227138, 2022). "In agreement with aberrant Wnt/β-catenin signaling, the gene expression of FHL2 has been shown to be dysregulated in a wide variety of cancers." (PMID 36227138, 2022). "FHL2 also shows a great potential to diagnose malignancies, become a therapeutic target and predict prognosis of cancer." (PMID 36227138, 2022). "Specificity protein 1 (SP1), an essential transcription factor in many cancer cells, has also been shown to regulate FHL2 expression by binding upstream of the FHL2 transcription start site." (PMID 34685595, 2021). "Transfection of HT-29 cells with miR-340-5p mimic not only decreased serum-induced expression of FHL2 but also decreased cancer cell migration and invasion." (PMID 34295384, 2021). "Confocal microscopy revealed that serum stimulation increased FHL2 levels in the cytoplasm of the cancer cells, and miR-340-5p mimic treatment reduced FHL2 levels." (PMID 34295384, 2021). "Membrane EpCAM is cleaved in cancers and its intracellular domain (EpICD) is transported into the nucleus and binds β-catenin, FHL2, and LEF1." (PMID 34209658, 2021). "Knowing that FHL2 expression is different in different cancer types, we decided to analyze one large dataset (GSE103512) containing four different cancer types." (PMID 34295384, 2021). "Convincing data has suggested that four and a half LIM domain 2 protein (FHL2) serves a key function in cancer cell metastasis and that microRNA (miR)-340-5p can regulate cancer cell migration." (PMID 34295384, 2021). "FHL2 has been demonstrated to play important roles in the cancer process including proliferation, differentiation and migration." (PMID 34295384, 2021). "Accumulating data suggest that FHL2 oncogene plays an important role in cancer cells migration and invasion." (PMID 34295384, 2021).
cancer (continued). "Four and a half LIM domain 2 protein (FHL2) is a multifunctional oncoprotein involved in cancer progression and metastasis." (PMID 34295384, 2021). "FHL2 expression and function have been studied in a number of diseases, including various types of cancer, cardiovascular disease, and overall metabolism." (PMID 34685595, 2021). "To further examine the downstream target protein of FHL2 we examined E-cad expression, which is known to regulate cancer cell metastasis." (PMID 34295384, 2021). "Blocking of the target site using a specific blocker reverted miR-340-5p mimic-induced inhibition of FHL2 expression and cancer cell migration and invasion." (PMID 34295384, 2021). "In a number of cancer cells, FHL2 protein has been described to function either as a tumor suppressor or as an oncoprotein." (PMID 34685595, 2021). "FOXK1 located mainly in the nucleus, and FHL2 disseminated at both the nucleus and cytoplasm of the same cancer cells." (PMID 27892920, 2016). "To validate our findings in vivo, we detected KLF8 and FHL2 expression in 13 pairs of adjacent normal colon mucosal tissues and cancer tissues by immunohistochemistry (IHC)." (PMID 26320172, 2015). "To elucidate the correlation between KLF8 and FHL2 in cancer cells, we first checked the expression of these proteins in CRC cell lines by western blot." (PMID 26320172, 2015). "Observations using serial sections showed that KLF8 and FHL2 were distributed in both the nucleus and cytoplasm of the same cancer cells." (PMID 26320172, 2015). "The variable expression of FHL2 in cancer cells is likely related to its distinct roles depending on the cell type in relation with FHL2 interaction with other proteins, causing either repression or activation of target genes." (PMID 23383046, 2013). "FHL2 suppression inhibits anchorage-independent growth of cancer cell lines and tumor formation in immuno-compromised mice." (PMID 20442768, 2010). "Although FHL2 activation has been found in various human cancers, evidence of its functional contribution to carcinogenesis has been lacking." (PMID 20442768, 2010). "In keeping with a previous report, FHL2 protein, undetectable in normal tissues, was expressed in all high-grade dysplasia and carcinomas analyzed (compare a with c and d)." (PMID 20442768, 2010). "In line with its effects on cell growth, overexpression of FHL2 has been detected in various types of cancer." (PMID 19018287, 2008). "The up-regulation of FHL2 observed in human cancers suggests a potential role of FHL2 in the oncogenic process." (PMID 19018287, 2008). "This suggests that understanding the function of FHL2 may be potentially important for cancer therapy." (PMID 39129787, 2024). "FHL2 overexpression exhibited same results on malignant phenotypes of cancer cells." (PMID 35281110, 2022). "The function of FHL2 in cancer is especially intriguing because it may function as a tumor inhibitor or an oncogenic protein." (PMID 36227138, 2022). "Four and a half LIM domains protein 2 (FHL2) which is known to play role in development and progression of different types of cancer via activation of androgen receptor (AR or NR3C4), Wnt/β-catenin pathway or several genes was demonstrated as target of miR-195-5p." (PMID 35281110, 2022). "Similarly, several studies investigate the modulation of FHL proteins as novel therapeutic strategies, either through the use of miRNA or shRNA that target FHL2 (mostly as a cancer therapy), or through FHL1 overexpression (to treat muscular dystrophy)." (PMID 34745373, 2021). "FHL2 is also shown to regulate cytoskeleton changes in cancer cells." (PMID 34295384, 2021). "However, the literature on FHL2 expression in different cancer types is somewhat complicated and partly contradictory." (PMID 34295384, 2021). "Furthermore, we found that miR-340-5p has a functional binding site on FHL2 mRNA and that targeting of FHL2 with miR-340-5p mimic reduces cancer cell migration and invasion." (PMID 34295384, 2021).
cancer (continued). "Hence, FHL2 plays an important role in cancer cell invasion and migration through multiple different mechanisms." (PMID 34295384, 2021). "Interestingly, in several cancer types high levels of nuclear FHL2 correlate with disease progression towards a malignant state." (PMID 32346031, 2020). "Recently, the role of FHL2 in cancers has become increasingly clear, including OC." (PMID 32774164, 2020). "We found in cancer cells that endogenous p57 and FHL2 are in a complex." (PMID 32346031, 2020). "FHL2 also interacts with a microtubule-associated protein 1 light chain 3 (LC3) regulating the development of skeletal muscle cells, and with β-catenin to upregulate its transactivation activity in cancer cells." (PMID 32256309, 2020). "This indicates that FHL2 dependent transcription contributes to cancer development and progression." (PMID 32346031, 2020). "Recently, the role of FHL2 in the activity of cancers has been mentioned a lot." (PMID 32774164, 2020). "The expression level and function of FHL2 are significantly different in various types of cancers, indicating that FHL2 works either as an oncogene or as a tumor suppressor gene in the occurrence and development of cancers, depending on different communicating partners." (PMID 28402264, 2017). "Interestingly, FHL2 is upregulated in many cancers compared with normal tissues, for example, human melanoma, breast cancer and pancreatic cancer." (PMID 28402264, 2017). "We observed that FOXK1 and FHL2 had higher expression in cancer samples." (PMID 27892920, 2016). "The role of FHL2 in cancer is particularly intriguing because FHL2 binds to different proteins." (PMID 26320172, 2015). "Few experimental studies suggest that FHL2 may play a role in cancer cell invasion and migration in some soft tissue cancers." (PMID 23383046, 2013). "We therefore investigated whether the inhibition of tumor growth induced by FHL2 silencing is related to decreased cancer cell replication." (PMID 23383046, 2013). "Interestingly, barely detectable in low-grade dysplastic tissues, FHL2 was significantly increased in high-grade dysplasia and cancer cells (compare b with c and d), showing a progressive expression pattern." (PMID 20442768, 2010). "Altogether, these results support the view that the intensity and localization of FHL2 expression in cancer cells may serve as a biomarker in classifying tumor stage and predicting disease outcome." (PMID 20442768, 2010). "Moreover, cellular localization of FHL2 switches from predominant cytoplasmic expression in high-grade dysplasia to enhanced nuclear accumulation in cancer cells." (PMID 20442768, 2010). "Moreover, contrasting markedly with the predominant cytoplasmic localization in high-grade dysplasia, intense nuclear accumulation of FHL2 protein was observed in carcinomas." (PMID 20442768, 2010). "Taken together, the function of FHL2 as a mechanotransducer appears to be important for understanding the links between mechanical effects on adhesion complexes and gene expression in the cancer cell, which may contribute to new insights for cancer therapy." (PMID 39129787, 2024). "However, distinguishing the function of FHL2 may be important when considering FHL2-targeted cancer therapy, as a strategy of cancer therapies generally depends on the stage of cancer, in which case FHL2 may have different functions at different cancer stages." (PMID 39129787, 2024). "This instance suggests that FHL2 may serve as a potential target for cancer therapy." (PMID 36004205, 2022). "Thus, FHL2 participates in various protein complexes regulating cell growth, differentiation and cytoskeletal remodeling as reported in immune cells and in the pathogenesis of numerous cancers." (PMID 32256309, 2020). "However, more research is needed to understand the role of FHL2 in other cancers." (PMID 33092075, 2020). "Thus, it appears that FHL2 can regulate tumorigenesis in multiple human cancers." (PMID 26320172, 2015).
cancer (continued). "FHL2 was found to be down-regulated in some cancers and to be elevated in others compared to normal tissues, suggesting that FHL2 may act as an oncoprotein or a tumor suppressor, depending on its role as transcriptional activator or repressor in the cell type in which it is expressed." (PMID 23383046, 2013). "In addition to involve Wnt proteins, the anti-oncogenic effect of FHL2 silencing may involve decreased interaction of FHL2 with integrins which are also critical for cancer cell adhesion to extracellular matrix, migration and invasion." (PMID 23383046, 2013). "Treatment targeting FHL2 may thus provide a viable and specific strategy for cancer therapy." (PMID 19018287, 2008). "In recent years, increasing studies have confirmed that m6A methylation‐related genes, such as ALKBH5, FHL2, DGCR8, YTHDF2, YTHDF3, and PICM8, were overexpressed in tumor tissues and closely related to malignant tumors." (PMID 33264518, 2021). "While a crucial contribution to cancer cell therapy resistance has been reported by us for several FAP, such as β1 integrin, LIMS1, FAK and FHL2, here we identified a number of novel candidates." (PMID 32605308, 2020). "FHL2, a member of the four and a half LIM domain family, has been shown to serve either as an oncoprotein or as a tumor suppressor in various cancers." (PMID 33092075, 2020). "Our previous results showed that FHL2 induced tumor cell EMT and maintained the invasive potential of cancer cells." (PMID 26320172, 2015). "We showed that FHL2 and KLF8 were expressed at high and intermediate levels, respectively, in the cytoplasm and nucleus of cancer cells." (PMID 26320172, 2015). "Although FHL2 silencing reduces cancer cell migration and invasion, there is no direct evidence that FHL2 contributes to cell migration and invasion as an adhesion component." (PMID 39129787, 2024). "The protein subnetwork of PIK3R2 could be used for further pan-cancer studies in the future: DUSP10, DUSP6, FHL2, IRS2, PIK3R2, and RIPK2." (PMID 36329531, 2022). "The complicated role of FHL2 in cancer will not be described in further detail in this review." (PMID 34685595, 2021). "Some factors identified (e.g., NF-κB, STAT3, FOS) are known to be involved for transformation in our model, others (e.g., CEBPB, HIF1a, ETS2, FHL2, TCF7L2, and NFE2L2) have been described as oncogenes in other settings, and some proteins (BHLHE40 and MAFB) have not been well linked to cancer." (PMID 29802342, 2018). "In complex with FHL2 (four- and one-half LIM domains protein 2), β-catenin, and Lef-1 (lymphoid enhancer-binding factor-1), EpICD has been shown to induce the transcription of specific oncogenes, such as cyclins and c-myc, thereby promoting cancer cell proliferation." (PMID 23667256, 2013). "Moreover, it was found that co-transfection of miR-340-5p mimic and TSB, but not with control TSB, had significantly higher invasion and migration of cancer cells, suggesting that miR-340-5p inhibits cancer cell migration and invasion by targeting a specific binding site at the 3′-UTR of FHL2 mRNA." (PMID 34295384, 2021).
tumor (35 papers, 2004 to 2025). "In our study, gain- and loss-of-function experiments demonstrated that FHL2 promotes the proliferation, migration, invasion, and tumor growth of LUSC both in vitro and in vivo." (PMID 40482916, 2025). "The FHL2 protein is localized in adhesion plaques, the cytoplasm, and the nucleus, where it interacts with a broad array of TFs and tumor-associated proteins." (PMID 40873580, 2025). "In this scenario, tumor cells with activated EpCAM i.e. the released EpICD associates with FHL2, β-catenin which form a nuclear complex with Lef-1 and induces transcription of genes associated with cell proliferation." (PMID 28903370, 2017). "AAV encoding small hairpin RNA (shRNA) targeting LMP-1 and FHL2 have been well employed in a variety of tumor models." (PMID 27009837, 2016). "Others have shown that FHL2 deficiency impairs bone remodelling, epithelial-mesenchymal transition, liver regeneration and invasion of tumour cells." (PMID 24260575, 2013). "Using a genetic approach, we demonstrate that loss of FHL2 significantly suppresses tumor multiplicity in ApcΔ14/+ mice." (PMID 20442768, 2010). "We therefore conclude that loss of FHL2 suppresses tumor formation in the intestine by probably acting on the initiation of tumors." (PMID 20442768, 2010). "As FHL2 plays an important role in cell proliferation, it is possible that high level of cyclin D1 may counteract FHL2 deficiency in the stimulation of tumor cell growth in ApcΔ14/+FHL2−/− mice." (PMID 20442768, 2010). "As accelerated cell migration by chemopreventive agents has been reported to be beneficial for eliminating deleterious cells, the tumor suppression function of FHL2 deficiency may be achieved in part through acceleration of cell migration in ApcΔ14/+ mice." (PMID 20442768, 2010). "Gain and loss experiments demonstrated that FHL2 promotes LUSC cell proliferation, migration, and invasion in vitro, while xenograft models confirmed its role in tumor growth in vivo." (PMID 40482916, 2025). "Conversely, FHL2 knockdown led to a marked reduction in tumor size and a significant inhibition of tumor growth." (PMID 40482916, 2025). "Patients with primary tumor seemed to have lower FHL2 expression levels than patients with recurrent tumor (P = 0.74), but further studies need to be conducted due to only 2 patients with recurrent tumor." (PMID 36227138, 2022). "With regard to residual tumor, 4 groups had similar FHL2 expression, while R2 had the higher FHL2 expression level compared to the other groups." (PMID 36227138, 2022). "Basal and stimulated expression of FHL2 appears to be highly influenced by the tumor cell type, tumor origin, and context." (PMID 34685595, 2021). "FHL2 can function as an oncoprotein or as a tumor suppressor in a tissue or cell type–dependent manner." (PMID 33092075, 2020). "Collectively, DLX6-AS1 knockdown inhibited tumor growth in vivo by inducing FHL2 expression via mediating miR-195-5p." (PMID 32774164, 2020). "The immunochemistry staining revealed that FHL2 expression was significantly increased in tumor tissue when compared with normal ovarian tissue." (PMID 33092075, 2020). "DLX6-AS1, as an oncogene in OC, accelerated tumor progression by up-regulating FHL2 via mediating miR-195-5p, suggesting that DLX6-AS1 was a hopeful target for the lncRNA-targeted therapy in OC." (PMID 32774164, 2020). "The FHL2 protein level in the GCT tumor cells significantly increased compared with the age-matched normal control tissues." (PMID 27415427, 2016).